DPP4 (dipeptidyl peptidase 4)
Diseases named in the same sentence as DPP4 in open-access papers (continued):
Sharing a sentence is not in itself a finding about the gene and the disease.
cancer (continued). "An unexpected and novel finding was the active shedding of inactivated DPP4 from cancer cells under hypoxic growth, which was mediated in part by an increase in MMP activity." (PMID 33143089, 2020). "In this study, we did landscape profiling of CoV receptors (viz ACE2, TMPRSS2, ANPEP, ENPEP, and DPP4) in various normal and cancer cells." (PMID 33330620, 2020). "DPP4 can regulate the bioactivity of several chemokines to influence immune and inflammatory responses critical to cancer progression." (PMID 33143089, 2020). "Of note, it has been reported that anti-DPP-4 monoclonal antibody or vildagliptin, a DPP-4 inhibitor, suppressed cancer cell growth and metastasis in both in vitro and in vivo studies." (PMID 32084231, 2020). "DPP-4 inhibitors have been shown to influence cancer cells by altering proliferation, apoptosis, extracellular matrix remodeling, and the response to chemotherapy." (PMID 33256016, 2020). "Apart from the use of these drugs in the management of DM‐II, the role of DPP4 inhibitors in cancer biology has been a topic of interest in many studies." (PMID 31124302, 2019). "After primary analysis, we performed further analysis to identify any other demographic, treatment, or cancer‐related variable that was significant in patients on DPP4 inhibitors." (PMID 31124302, 2019). "This SEER‐Medicare study further establishes the role of DPP4 inhibitors as cancer inhibitory, especially in combination with metformin." (PMID 31124302, 2019). "Regarding the results observed in the serum levels of DPP-4, from the initial report as a possible biomarker in inflammatory processes or cancer, a great variability of results has been observed according to the pathology studied and its temporality." (PMID 31100960, 2019). "When DPP4 inhibitors were used in combination of metformin which is known to suppress cancer, the survival advantage was even more pronounced (HR of 0.83; CI: 0.77‐0.90, P < 0.0001)." (PMID 31124302, 2019). "The factors regulating the expression and tissue distribution of DPP-4 have been studied in several types of cancer, and it has been observed that hypoxia increases the surface levels of DPP-4." (PMID 29507662, 2018). "DPP4 has been related to increased proportion of cancer stem cells and worse prognosis of CRC patients." (PMID 30450337, 2018). "It is probable that, under different microenvironments, DPP4 has diverse roles in the carcinogenesis of various carcinomas." (PMID 27936466, 2017). "There was also a trend towards up-regulation of CA2, DPP4 and IL1RL1 in cancer associated fibroblasts." (PMID 23497279, 2013). "Both luminal and cancer cells are strongly immunostained for CD26, but the signal counts for DPP4 were generally low." (PMID 23029164, 2012). "However, available data on DPP4 inhibition and its influence in cancer therapy are controversial and scarce." (PMID 42193050, 2026). "However, other studies indicated a probable role of DPP4 inhibitors in cancer progression, proposing malignancies as one of the undesired side effects of DPP4 inhibitors." (PMID 39861115, 2025). "DPP-4 enzyme is an essential biomarker in cancer disease biology." (PMID 40786041, 2025). "However, a retrospective cohort study indicates that the group treated with SGLT2 inhibitors had a lower incidence of cancers than the group treated with dipeptidyl peptidase-4 inhibitors which are known to increase blood GLP-1 levels." (PMID 39940750, 2025).
cancer (continued). "DPP-4 inhibitors (DPP-4is) also present a dichotomy in cancer outcomes." (PMID 40282969, 2025). "DPP-4 inhibitors have been demonstrated to boost the anti-cancer effects of immunotherapy." (PMID 39390508, 2024). "While preclinical studies raised concerns about a possible link between DPP-4 inhibition and increased cancer risk, clinical meta-analyses did not substantiate these findings." (PMID 39595655, 2024). "They reported that DPP-4 inhibitors may promote cancer progression via induction of the CXCL12/CXCR4/mTOR axis, which is also important for vascular damage in cancer tissue." (PMID 39135967, 2024). "However, the following article on DPP4 inhibitors and malignant tumors is considered an interesting pathogenesis." (PMID 39135967, 2024). "This certainly supported our assumption that DPP-4 inhibitors might have a preventive effect on cancer." (PMID 38758855, 2024). "Dipeptidyl peptidase 4 (DPP-4) is a promising biomarker for cancer and metabolic diseases." (PMID 39439401, 2024). "Taken together, these results highlight the crucial role of DPP4 and YAP1/TEAD in driving the emergence of ECM-myCAF from Detox-iCAF through two independent mechanisms, shedding light on the molecular interactions underlying cancer immune escape." (PMID 38561380, 2024). "Furthermore, we investigated the effect of DPP4 knockdown on the biological behavior OV cancer cells." (PMID 37907650, 2023). "However, just to give few examples biguanides, DPP-4-inhibitors and Thiazolidinediones were found to exert strong anti-cancer effects in TC." (PMID 38146457, 2023). "We have provided clear evidence suggesting that DPP-4 inhibition could facilitate cancer growth, metastasis, and chemoresistance via the accumulation of CXCL12, the endogenous substrate of the DPP-4 enzyme." (PMID 37760498, 2023). "Previous studies showed that DPP4 expression levels were significantly altered in tumors and might play a vital role in cancer development." (PMID 37907650, 2023). "Another population-based cohort study of patients with T2DM with a concomitant cancer showed that no increased risk of metastasis was associated with DPP-4 inhibitor therapy." (PMID 38146457, 2023). "The effect of DPP4 on cell migration appears different in different cancer types." (PMID 37907650, 2023). "Our previous study showed that both adenosine derivatives, N6, N6-dimethyladenosine, CD, adenosine-inhibited DPP4/CD26 expression in cancer cells, and adenosine further revealed that it significantly suppresses the expression of the lymphocyte activating factor 3 (Lag3) in mice with AD injection." (PMID 38138098, 2023). "DPP4 can be either up‐ or downregulated in various cancer types." (PMID 37533175, 2023). "Our findings suggest that DPP-4 inhibitor, one of the most prescribed anti-diabetic drugs, could harm patients with certain cancers." (PMID 37760498, 2023). "Our study suggests that TREM1, MAPK1, MAPK8, CTSB, MIF, and DPP4 proteins may be targeted by compounds in medicinal plants for their anti-cancer effects." (PMID 37454152, 2023). "Metformin counteracts such an undesirable influence of DPP-4 inhibition on cancer biology." (PMID 37760498, 2023). "In vivo post-translational modification of chemokines by DPP4 exerts an inhibition on the migration of T cell to tumors and DPP4 inhibition might therefore be a useful adjuvant treatment for immunotherapy in cancer patients." (PMID 36795572, 2023). "The combination with metformin use could provide some clues to the use of DPP-4 inhibitors via the modulation of cancer autophagy-dependent survival signaling." (PMID 37760498, 2023). "When blocked by its inhibitor DPP-4i, the effect of DPP-4 on cancer will be attenuated or reversed." (PMID 35933633, 2022). "However, in the early progression steps of this and other cancers, sCD26/DPP4 levels are lower than in healthy donors." (PMID 36230486, 2022).
cancer (continued). "DPP-4 has sparked scientific interest over the last 10 years, with numerous studies describing its role in tumor immunology and the prognosis of patients with cancer." (PMID 35317435, 2022). "The role of DPP4 has been extensively studied in several cancers." (PMID 35733175, 2022). "We also found that DPP4 interacts with number of cancer-related genes." (PMID 36071454, 2022). "Thus, overall, DPP4 performs multiple activities in metabolism, cardiovascular system, immunology, endocrinology, fibrosis, and cancer." (PMID 36009573, 2022). "Thus, we next estimated the expression profiles of the potential SARS-CoV-2 receptor DPP4 in pan-cancers." (PMID 33614513, 2021). "A meta-analysis of randomized clinical trials showed that DPP-4 inhibitors were not related to an increased risk of developing cancers compared to a placebo or other anti-diabetic drugs in T2DM patients." (PMID 34063285, 2021). "The results showed that DPP4 expression significantly correlated with infiltration of CD8+ T cells, CD4+ T cells, Treg, B cells, NK cells, dendritic cells, neutrophils, macrophages, monocytes, and cancer-associated fibroblasts in pan-cancer patients." (PMID 33614513, 2021). "LUAD has been reported as the most frequent cancer type in patients infected with COVID in terms of malignancies, and elevated DPP4 was detected consistently in LUAD patients and correlated with patient age, individual cancer stage, and nodal metastasis status." (PMID 33614513, 2021). "An elevated level of these substrates of DPP-4 can potentially influence cancer progression." (PMID 34063285, 2021). "Animal experiments and clinical trials should be conducted in the future to evaluate whether DPP4 inhibitors have therapeutic potential in preventing or alleviating SARS-CoV-2 infection in obese or specific cancer patients." (PMID 33614513, 2021). "Other meta-analyses also reported that DPP-4 inhibitors did not increase the risk of cancers of the digestive system or overall cancers." (PMID 34063285, 2021). "CD26/DPP4 also has a well-established role in cancer metastasis." (PMID 34055551, 2021). "We next examined the efficiency of DPP4 in the survival of pan-cancer patients with TIMER." (PMID 33614513, 2021). "This clinical evidence suggests the effect of a DPP-4 inhibitor on cancer progression in T2DM patients with certain cancers differs depending on whether it is co-prescribed with metformin." (PMID 34063285, 2021). "Expression of DPP4 in different types of cancer compared with normal samples." (PMID 33614513, 2021). "The distinct role of DPP4 in these specific cancers might be due to the particular distribution of DPP4 in different cell types." (PMID 33614513, 2021). "Available clinical evidence has indicated no clear association as yet between DPP-4 inhibitors and cancer incidence or prognosis in diabetic patients." (PMID 34063285, 2021). "Thus, further mechanistic investigations about the link between DPP-4 inhibitors and cancer biology, especially in diabetic conditions, are an essential research topic in both diabetology and oncology." (PMID 34063285, 2021). "The DNA methylation level of DPP4 was further analyzed in several types of cancer." (PMID 33614513, 2021). "DPP4 is differentially expressed in chronic liver diseases and cancers in humans." (PMID 34771657, 2021). "Given its diverse functions, it is not surprising that dysregulation of the expression or the enzymatic activity of CD26/DPP4 might contribute to cancer development." (PMID 34885056, 2021). "Some preclinical studies showed that DPP4 inhibitors could suppress the growth of a number of cancer cell lines." (PMID 34926239, 2021). "Indeed, dipeptidyl peptidase 4 (DPP4), fibroblast activated protein (FAP), and collagen type XI (COL11A1), markers of activated/cancer-associated fibroblasts, are expressed at very low levels." (PMID 33413690, 2021). "Adding to the multifaceted role of DPP4 is its role in the TME in human cancers." (PMID 34055551, 2021).
cancer (continued). "Although angiotensin converting enzyme II (ACE2) has been identified as a cellular binding receptor for SARS-CoV-2, immunopathological changes in severe cancer patients support the investigation of additional potential receptors such as dipeptidyl peptidase 4 (DPP4), a key immunoregulator." (PMID 33614513, 2021). "Though the exact mechanism is unknown, there have been numerous proposed mechanisms for the role of DPP4 in cancer." (PMID 34055551, 2021). "Nevertheless, the currently available clinical study indicated that there is no significant risk of a cancer prognosis and metastasis among cancer-bearing diabetic patients on DPP-4 inhibitor therapy." (PMID 34063285, 2021). "In addition to the promising effects in DM-II treatment, increasing studies have examined the role of DPP4-inhibitors in cancer development and treatment." (PMID 34298800, 2021). "DPP4 can work on many types of cells, including T lymphocytes, adipocytes, hepatocytes, and smooth muscle cells, which triggers metabolic and immune responses in cancer patients." (PMID 33614513, 2021). "However, DPP4 abundance and activity vary between different cancer types, and exhibit complex patterns of regulation." (PMID 33143089, 2020). "In the present study, we investigated whether DPP-4 inhibitors might affect AKI outcomes in diabetic-cancer patients treated with high-dose cisplatin." (PMID 32084231, 2020). "DPP4 plays an important role in cancer progression and metastasis." (PMID 32498358, 2020). "DPP4 is widely expressed on endothelial, epithelial and immune cells in mammalian tissues and has multifunctional roles in metabolism, immunology, endocrinology, fibrosis and cancer." (PMID 33218025, 2020). "The use of DPP-4 inhibitors could improve the renal outcome after cisplatin treatment in diabetic-cancer patients." (PMID 32084231, 2020). "Therefore, higher CXCL12 levels in response to DPP4 inhibitor treatment can be relevant to the metastasis of CXCR4-positive cancers." (PMID 32498358, 2020). "The measurement of specific, proteolytic DPP4 fragments shed by cancer cells may thus be more relevant as a biomarker of disease status." (PMID 33143089, 2020). "We hypothesized that DPP-4 inhibitors can prevent cisplatin-induced AKI in diabetic-cancer patients." (PMID 32084231, 2020). "Our data show that the usage of DPP-4 inhibitors to diabetic-cancer patients could reduce the incidence of cisplatin-induced AKI from 64% to 25%, but its preventive measure is still insufficient." (PMID 32084231, 2020). "CD26 and/or dipeptidyl peptidase 4 inhibitors have already shown anti-metastatic effects in pre-clinical models, and the existence of these CD26+ subsets may help further research against cancer metastasis." (PMID 31285270, 2019). "A recent review on the potential association between DPP-4 inhibitor use and cancer did not reveal an increased cancer risk including pancreatic cancer." (PMID 31275246, 2019). "Certain cancers also exhibit high expression of DPP4 as exemplified by the adenocarcinoma cell line in this study and this may provide a measure of cancer activity and response to therapy." (PMID 30894647, 2019). "In addition, in cancer biology research, circulating DPP4 activity was demonstrated to be a therapeutic target and biomarker for several cancers." (PMID 27654253, 2016). "In conclusion, this meta-analysis seemed to exclude any relevant short-term effect of DPP4-inhibitors on the incidence of cancer and suggested a possible protection from MACE, but the result should be interpreted with caution, as those events were not the principal endpoints." (PMID 23710467, 2013). "Therefore, nanobody-DPP4 fusions degrade cancer-derived sICOSL to reverse CTL dysfunction." (PMID 40708008, 2025). "Therefore, also in this context, further watchful observation seems reasonable, though their insulinotropic action puts DPP-4 inhibitors not high on the list of preferred diabetes medications in patients at risk of cancer." (PMID 40277890, 2025).
cancer (continued). "Therefore, nanobody-DPP4 fusions specifically target cancer cells to degrade sICOSL." (PMID 40708008, 2025). "Similarly, a retrospective analysis of metastatic RCC found no substantial clinical benefit from DPP-4 inhibition, further highlighting the variability in cancer-related outcomes associated with these drugs." (PMID 39595655, 2024). "On the other hand, the investigation of DPP-4 inhibitors as potential anti-cancer agents was not discouraged by this study because DPP4 expression in TC was demonstrated to be associated with cellular invasion, promoting TC cell metastasis, and a more aggressive disease in papillary TC." (PMID 38146457, 2023). "The potential influence of DPP-4 suppression on cancer biology remains unknown." (PMID 37760498, 2023). "However, most results have been obtained only in experimental animal models, and some issues, such as whether DPP4 has an inhibitory or promotive effect on cancer metastasis, are controversial." (PMID 35053615, 2022). "However, DPP4 inhibitors may promote cancer progression through inhibition of chemokine posttranscriptional modification if the targeted chemokines enhance cancer progression." (PMID 35053615, 2022). "However, there is reason to consider DPP4 as a potential cancer target." (PMID 35158824, 2022). "Although caution has to be taken when targeting DPP4 for the treatment of cancer, DPP4 inhibitors tested in clinic so far have proved to be safe therapeutics, and they deserve further exploration in combination treatments of cancers with an unmet clinical need." (PMID 35158891, 2022). "Therefore, inhibiting CD26/DPP4 has been proposed to delay cancer cell invasion or metastasis." (PMID 34055551, 2021). "Therefore, we investigated whether DPP4 expression was correlated with immune infiltration levels in various cancer types from TIMER." (PMID 33614513, 2021). "In addition, a previous meta-analysis found that patients with type 2 DM who were treated with DPP-4 inhibitors did not have a higher risk of developing cancer than those who received other drugs or a placebo." (PMID 34604157, 2021). "Therefore, the repurposing actions of DPP4 inhibitors may serve as an alternative intervention in cancer treatment." (PMID 34926239, 2021). "However, introducing the general aspect of the biology of the DPP-4 gene family on cancer could help to understand the whole picture of this interesting peptidase family regarding cancer biology." (PMID 34063285, 2021). "However, more clinical studies are needed to address the role of CD26/DPP4 expression in TIL especially with respect to their role in the induction of effective immune responses and durable remissions following cancer immunotherapy and to unravel the underlying mechanisms in detail." (PMID 34885056, 2021). "Blocking the DPP4 activity may thus lead to delayed propagation of cancer cells." (PMID 32296640, 2020). "Therefore, the use of DPP-4 inhibitors may be one of supportive therapies for cancer patients treated with high-dose cisplatin." (PMID 32084231, 2020). "The alterations in DPP4 abundance and activity observed under hypoxic conditions may therefore be related to a transition state between transcriptionally plastic cell phenotypes, required to preserve or maintain cancer cell populations during hypoxic stress." (PMID 33143089, 2020). "The emerging roles of proteases, e.g., matrix metalloproteinases, cathepsins, and dipeptidyl peptidase 4, in chemokine inactivation define new resistance mechanisms against immunotherapies and identify attractive new targets to enhance immune intervention in cancer." (PMID 31482487, 2019). "Thus, DPP4 may play different roles in different backgrounds or cancers, and further studies are needed to elucidate the exact mechanism of DPP4 in cancer." (PMID 30450337, 2018).